LINC01214 (long independently transcribed non-coding RNA 1214)
Gene: Long non-coding RNA gene on chromosome 3 (150,265,407 to 150,409,594, reverse strand). Ensembl gene ENSG00000243550.
Diseases named in the same sentence as LINC01214 in open-access papers:
LINC01214 is named in the same sentence as 4 diseases in open-access papers, as found by Europe PMC text mining. Sharing a sentence is not in itself a finding about the gene and the disease. The quoted sentences say what the papers report.
lung carcinoma (1 paper, 2020). "When compared with the non-tumorigenic IMR-90, the expression of FEZF1-AS1, LIN00673 and LINC01214 was markedly higher in most lung cancer cell lines; the expression of PCAT6 and LINC01929 was strikingly lower and no clear trend was observed for the expression of NUTM2A-AS1." (PMID 32020063, 2020).
lymph node metastasis (1 paper, 2022). "Likewise, patients without lymph node metastasis were more likely to have low LINC01214 expression than those with lymph node metastasis (P = 0.032)." (PMID 35372012, 2022).
psoriasis (1 paper, 2021). An autoimmune condition characterized by red, well-delineated plaques with silvery scales that are usually on the extensor surfaces and scalp. "We found that LINC01137, LINC01215, MAPKAPK5-AS1, TPT1-AS1, CARMN, CCDC18-AS1, EPB41L4A-AS, and LINC01214 may be potential diagnostic biomarkers for psoriasis." (PMID 33732554, 2021). "LINC01137, LINC01215, and LINC01214 may serve as predictive biomarkers for biological response in psoriasis." (PMID 33732554, 2021). "Our findings suggest that LINC01137, LINC01215, MAPKAPK5-AS1, TPT1-AS1, CARMN, CCDC18-AS1, EPB41L4A-AS, and LINC01214 may be potential diagnostic biomarkers for psoriasis and LINC01137, LINC01215, and LINC01214 may serve as predictive biomarkers for biologics response in psoriasis." (PMID 33732554, 2021).
tumor (1 paper, 2025). "Based on these results, it is proposed that LINC01214 is associated with tumor progression in NSCLC." (PMID 41209079, 2025).